MYD88 (MYD88 innate immune signal transduction adaptor)
Diseases named in the same sentence as MYD88 in open-access papers (continued):
Sharing a sentence is not in itself a finding about the gene and the disease.
tumor (continued). "TLR4 involved in tumor occurrence and development by inducing M2 macrophage infiltration and angiogenesis in tumor microenvironment and participating in the process of apoptosis, MyD88-dependent and independent signal transduction, or other biological processes." (PMID 32351566, 2020). "Therefore, it cannot be determined whether the contribution of MyD88 to tumorigenesis is critical only at the initiation stage of tumor formation or if it remains a key driver for the progression of tumor." (PMID 31303442, 2019). "Interestingly, addition of conditioned media of LLC cells or C26 adenocarcinoma induces the gene expression of several TLRs and MyD88 in cultured myotubes suggesting that factors produced by cachectic tumor cells upregulate the TLR-mediated signaling in skeletal muscle." (PMID 31817027, 2019). "Taken together, we substantiated that IL-36β could promote CD8+ T cell activation through activating mTORC1 dependent on PI3K/Akt, IKK and MyD88 pathways, leading to enhancement of antitumor immune responses, which laid the foundations for applying IL-36β into tumor immunotherapy." (PMID 31447838, 2019). "In summary, the current study demonstrated that IL-36β could promote CD8+ T cell activation and antitumor immune responses by activating mTORC1 through PI3K/Akt, IKK, and MyD88 pathways, and proved that IL-36β had potential application value in tumor immunotherapy." (PMID 31447838, 2019). "Particularly, TLR4 and its adaptor, myeloid differentiation primary response gene 88 (MyD88), were found to be essential for optimal antigen processing by inhibiting the fusion between phagosomes and lysosomes, thereby preventing the degradation of tumor antigens." (PMID 29462947, 2018). "In contrast, both the tumor tissue and the CSF ctDNA were negative for the MYD88 p.V217F mutation." (PMID 30294590, 2018). "Tumour released IL-1 cross-talks to TAMs and induces M2 polarization to an immunosuppressive phenotype via IL-1 receptor (IL-1R) and myeloid differentiation primary response gene 88 (MyD88), which requires I-kappaB kinase beta (IKKβ)-mediated nuclear factor kappa B (NF-κB)." (PMID 28381274, 2017). "Consequently, targeting TLR4/MyD88 signaling may be an attractive therapeutic strategy to hinder tumor progression." (PMID 28662055, 2017). "To clarify the detailed mechanism of anti-tumor immunomodulatory effects of APS and to verify whether APS activates TLR4 signaling pathway through MyD88-dependent pathway, we used C57BL/6J (MyD88+/+) and MyD88-deficient (MyD88−/−) tumor-bearing mice in this study." (PMID 28303957, 2017). "Although no experimental data is currently available for the four ERK2 mutations identified in this analysis, it is interesting to note that the tumor samples in which they have been identified did not have mutations in MYD88 or other TLR-related signaling network component." (PMID 27303665, 2016). "Therefore, the hypothesis proposed is that inhibition of ERK1/2 MAPK activation would prevent tumor growth downstream of MYD88[L265]." (PMID 27303665, 2016). "The tumour-inhibitory effect of ablating TNFR or MyD88 in radiosensitive leukocytes in InvEE mice was greater than that of TLR-5 ablation (0.01<P<0.05; one-way analysis of variance), suggesting that additional components of the immune system that converge on NF-κB may contribute." (PMID 25575023, 2015). "In addition, MYD88 promotes tumor cell proliferation via NF-κB activation." (PMID 24527027, 2014). "The TIR signaling pathway, primarily through its two major branches—the MyD88-dependent and TRIF-dependent pathways—regulates inflammatory responses, immune cell infiltration, and tumor cell biological behavior." (PMID 41488647, 2025). "In summary, we demonstrated that HMGB1 released from tumor cells treated with the recombinant adenoviruses ADVNE or ADVPPE binds to the TLR4 receptor on macrophages, activating the MyD88-NFκB-NLRP3 (ASC) pathway and inducing M1 macrophage polarization." (PMID 40082916, 2025).
tumor (continued). "Overexpression of TLR4 significantly enhances TLR4/Myd88/NF-κB/PD-L1 signaling and the apoptosis of CD8 + T cells, thereby facilitating tumor cell immune escape and reversing the regulatory effects induced by LINC00886 downregulation." (PMID 40999508, 2025). "In the context of anti-tumor immunity, TIR signaling initiates multi-tiered immune activation through both the MyD88 and TRIF pathways." (PMID 41488647, 2025). "Additionally, the antitumor effects of NaB were associated with the suppression of tumor cell proliferation and migration, an increase in the rate of tumor cell apoptosis, the modulation of the gut microbiota, and the inhibition of the HDAC/TLR4/MyD88 signaling pathway." (PMID 41251471, 2025). "Of these, five were present in at least one tumor from each cohort: IGLL5 p.L28M, MTMR1 p.R389Q, MYD88 p.S206C, PABPC3 p.K231E." (PMID 40634688, 2025). "In PDAC, gut-derived LPS (≥500 pg/mL in the TME) exerts dual effects: via TLR4/MyD88/AKT/NF-κB signaling, it upregulates tumor PD-L1 to promote immune evasion, yet recruits CD3+CD8+ T cells for antitumor activity." (PMID 41181090, 2025). "MyD88 was required for induction of IL-6 and TNF-α, activation of MDSCs, and tumor metastasis mediated by tumor-derived exosomes." (PMID 40443670, 2025). "Mechanistically, CD8α:MyD88 signaling increased ZAP-70, ERK1/2, JNK, and p38 activation, reducing the response threshold in tumor-specific CD8+ T cells." (PMID 40948803, 2025). "The pathway’s influence extends to tumor dissemination, with combined high TLR4/MyD88 expression correlating with lymph node metastasis." (PMID 40703545, 2025). "Both F. nucleatum and P. gingivalis activate the TLR/MyD88-triggered integrin/FAK pathway, enhancing tumor invasiveness." (PMID 40948759, 2025). "When HMGB1 is released from dying cells, the activated TLR4/MyD88 pathway enhances INF-β signal transduction, stimulates immune activity, and up-regulates the expression of PD-L1 in neighboring surviving tumor cells." (PMID 38785969, 2024). "MyD88 plays a critical role in tumor-derived exosome-mediated MDSC expansion and subsequent tumor metastasis." (PMID 38347830, 2024). "Sustained MyD88-IRAK signaling is essential for both ABC-DLBCL progression and tumor cell viability." (PMID 38792088, 2024). "In a CRC xenograft model, Xiaochai Hu Decoction suppresses tumor progression via gut microbiota modulation, implicating the TLR4/MyD88/NF-κB pathway." (PMID 38930793, 2024). "In the MYD88-mutant preclinical model of DLBCL, KT-413 was shown to have activity in inducing partial or complete tumor regression." (PMID 39169396, 2024). "These microbes activate the TLR4/MyD88 pathway in CRC, contributing to the delta-5 desaturase-arachidonic acid axis, metabolizing to PGE-2, and ultimately encouraging tumor growth." (PMID 38930793, 2024). "Our results showed that the gene expression of both MyD88 and TRAF6 increased significantly in the tumor-bearing groups when compared to the control groups." (PMID 39394174, 2024). "It balances tumor cell apoptosis and autophagy via the TLR4/MyD88 signaling pathway, promoting chemoresistance to 5-fluorouracil and oxaliplatin." (PMID 39545038, 2024). "An analysis of the tumor microenvironment indicated that CD36 and MYD88 were significantly positively correlated with several microenvironment scores, suggesting their role in promoting the formation of an immune-supportive environment." (PMID 38919626, 2024). "Blocking MyD88 with the novel inhibitor TJ-M2010-5 suppressed MDSC Arg1 and iNOS expression enhancing anti-tumour immunity." (PMID 38464388, 2024). "A dysregulation of the MyD88 gene and TLR signaling can contribute to chronic inflammation and immune activation within the tumor microenvironment." (PMID 38434966, 2024). "Upon detecting tumor antigens, TLR4 triggers the activation of MyD88 (myeloid differentiation factor 88), which in turn initiates the translocation of NF-κB to the nucleus, followed by the transcription of target genes." (PMID 39390599, 2024).
tumor (continued). "Researchers report that C21 steroidal glycosides can inhibit tumor cells by regulating the Wnt/β-catenin signaling pathway, TLR4/MyD88/NF-κB, AKT signaling pathway, PI3K/AKT/mTOR signaling pathway, and Hippo pathway." (PMID 36985801, 2023). "To further dissect the cell type specific mechanism of tumor promotion by TLR activation in a COPD setting, we studied the signaling checkpoints shared among TLRs, specifically MyD88/NF-κB signaling." (PMID 37283745, 2023). "In one study, inducible MyD88/CD40 (iMC) CAR NK cells were extended to CAR NK cells and enhanced the tumor killing efficacy of CAR-NK by increasing cytotoxic function, cytokine secretion and proliferation." (PMID 37510993, 2023). "Specifically, activation of CD8+ T cell MyD88 and JAK/STAT signaling was higher in closer proximity to the tumor, and M1 macrophages and monocytes showed stronger activation of pSTAT1 at the tumor front." (PMID 38125025, 2023). "CGP of PCL tissues revealed the tumor to be wildtype for CD79B, MYD88, CARD11, and TNFAIP3, with genomic alterations detected in SMO, CIITA, ETS1, HST1H1D, and SOCS1." (PMID 36342081, 2023). "As we have previously demonstrated that the immune response after systemic administration and tumor homing of the treatment play key roles in the improved antitumor effect, we also studied these parameters after treatment with OAd-MSC MyD88−/−." (PMID 36875156, 2023). "A previous study demonstrated that MYD88 detection by droplet digital PCR (ddPCR) can be utilized for MRD monitoring, which will become a feasible tool for tumor load screening." (PMID 37234167, 2023). "The activation of microglia (MG) and astrocytes (AS) was, however, reduced in both MyD88−/− and TRIF−/− brain slices, and fewer microglial cells moved into the tumor plug compared to the wild-type (WT) co-cultures." (PMID 36224342, 2022). "We appreciate that IFN-I signaling could be due to MYD88 signaling resulting from epigenetic re-expression of retroviral elements or from the response to genetic material from dying cells, and operates as a bridge between innate and adaptive anti-tumor immunity." (PMID 35634329, 2022). "In A549 lung cancer cells, inhibition of a flagellin-derived agonist delayed tumor growth through the TLR5 and MyD88-dependent pathway and even suppressed cell viability." (PMID 36389785, 2022). "The adjuvant mechanism of (R)-DOTAP is also related to TLRs, which targets TLR7 and TLR9 to induce the production of Myd88-dependent type I IFN, eventually leading to tumor regression." (PMID 35883176, 2022). "Signaling analysis of the tumor-derived versican-mediated TLR2 signaling identified TLR6 as necessary heterodimer and MyD88 as responsible TLR adapter." (PMID 36224342, 2022). "The expression of MyD88 was detected in approximately 70% of EOC patients, and it has been considered a significantly poor prognostic indicator of tumor." (PMID 35464826, 2022). "HMGB1 secreted by dying tumor cells triggers the activation of IFN-γ polarizing tumor-antigen specific T-cells through a TLR4- and MyD88-dependent mechanism." (PMID 35493517, 2022). "At 72 h, colon and tumour tissue were collected and examined for histopathological changes and RT-PCR for genes of interest; TLR4, MD-2, CD-14, MyD88, IL-6, IL-6R, CXCL2, CXCR1, and CXCR2." (PMID 35962138, 2022). "However, HMGB1 could promote the release of cytokines such as IL-6 and IL-8 by activating MAPK- and MyD88-dependent NF-KB pathways in the extracellular matrix, thus stimulating tumor cell proliferation, angiogenesis, epithelial-mesenchymal transition (EMT), invasion, and metastasis." (PMID 35273678, 2022). "Although the autophagy of B cells remains poorly understood in tumor pathogenesis, B cell activation is induced by tumor-derived autophagosomes (Dribbles), which sequester various tumor antigens in a TLR4/MYD88-dependent manner." (PMID 35321516, 2022).
tumor (continued). "The data indicate potential cardioprotective effects of preconditioning exercise on preserving cardiac structure and function, as well as regulating autophagic (beclin-1), inflammatory (TGF-β and MyD88), and atrophy (p-FOXO1) pathways during tumor bearing." (PMID 36531941, 2022). "The co-assembled peptide hydrogel vaccine effectively activated the MyD88-dependent NF-κB signaling pathway in DCs, displaying superior antitumor effect than Alum-adjuvanted epitope vaccine in E.G7-OVA tumor model." (PMID 35883176, 2022). "We found that MyD88 inhibitor administration reduced iNOS, Arg-1 and IDO expression to weaken tumor-immune evasion mediated by MDSCs." (PMID 35089465, 2022). "In CRC, a number of studies have confirmed that some molecules, such as MyD88, SREBP1, and CXCL5, promoted CRC cell proliferation, migration, invasion, and tumor growth through NF-κB activation." (PMID 35309901, 2022). "Activation of MyD88- and TRIF-dependent pathways result in the production of chemokines, such as CXCL10 or CCL5, engaging immune cells and inducing anti-tumor immunity." (PMID 34572948, 2021). "We confirmed previously reported alterations in several components of the NF-κB signaling, including TNFAIP3A (26%), MYD88 (12%), and BCL10 (7%), which were observed in 52 tumor specimens." (PMID 35528192, 2021). "The content of serum MMP-2, tumor tissue TLR4, MYD88 were also reduced by Andro treatment with statistical implications (p < 0.05)." (PMID 33967748, 2021). "However, in barrier-protected tissues where tumor cells experience less antigenic stimulation, NF-κB pathway activation is particularly dependent on chronic B-cell receptor signaling and Toll-like receptor signaling maintained by CARD11, CD79B, and MYD88 mutations." (PMID 33747936, 2021). "Herein, we decided to investigate the role of four different MyD88-dependent single TLRs (TLR2−/−, TLR4−/−, TLR7−/− and TLR9−/−) in BCG tumor treatment." (PMID 34341449, 2021). "We evaluate BCG intratumoral treatment in a subcutaneous MB49 tumor model using different knockout (KO) mice (STING−/−, cGAS−/−, TLR2−/−, TLR3−/−, TLR4−/−, TLR7−/−, TLR9−/−, TLR3/7/9−/−, MyD88−/−, IL-1R−/−, Caspase1/11−/−, Gasdermin-D−/− and IFNAR−/−)." (PMID 34341449, 2021). "Survival function estimated by Kaplan-Meier method was stratified by MYD88, sex, age, treatment, KPS, tumor location, and tumor extent." (PMID 34377990, 2021). "Mechanistically, the ability of IL-33 to induce tumor-reactive IFN-γ+ CD107+ CD8+ T and NK cells was recently shown to be dependent on MyD88 signaling in a mouse model of Lewis lung carcinoma." (PMID 33329534, 2020). "In fact, the innate MyD88 signaling pathway and FcγR were involved in therapeutic effect of Cetuximab, and CD8+ T cell depletion diminished Cetuximab mediated tumor regression." (PMID 32605193, 2020). "Our findings, therefore, raise the possibility that ETS1 amplifies the tumor-promoting effects of these mutants by increasing their expression and, indeed, ETS1 gains are common in the ABC-DLBCL cluster 5 characterized by MYD88 and CD79A/B." (PMID 32679859, 2020). "We then analyze the relationship between MyD88 expression and clinicopathologic features of GCC patients including gender, size of the tumor, lymph node metastasis, histological grade, depth of tumor invasion, and TNM stage." (PMID 32477927, 2020). "In parallel, ApcMin/+/MyD88−/− mice showed similar phenotype proposing that RAGE and MyD88 signaling share tumor-promoting mechanisms." (PMID 33117687, 2020). "Although MyD88 signalling reduced VSV replication, it also reduced viral dissemination from the tumour." (PMID 32882969, 2020). "For this, wild-type and MyD88−/− mice were implanted with B16F10 melanoma cells, treated with MIP and monitored for tumor growth." (PMID 31590685, 2019). "Wild-type and MyD88−/− mice were implanted with B16F10 tumor cells, treated with MIP or phosphate-buffered saline (PBS) and monitored for tumor growth." (PMID 31590685, 2019).
tumor (continued). "In the present study, we further examined the role of MyD88 and TLR2 in MIP-mediated tumor regression." (PMID 31590685, 2019). "Lymphocytes also utilize the MyD88 pathway, but their participation, if any, in antitumor CTL proliferation for tumor regression appears to be minimal, at least in this tumor model." (PMID 29593736, 2018). "Inducible MyD88/CD40 is an activation switch that supports NK cell expansion, persistence and anti-tumor activity in vitro and in vivo when paired with autocrine IL-15 expression." (PMID 30400835, 2018). "TLR4 and MyD88 have been demonstrated over expression in breast cancer, suggesting the possible role of TLR4 signaling pathway in tumor microenvironment." (PMID 29029545, 2017). "B cell activation is induced by tumor-derived autophagosomes (Dribbles), which sequester various tumor antigens in a TLR4/MYD88-dependent reaction." (PMID 28771183, 2017). "According to the previous literatures, Myd88 was documented as a tumor promoter in various cancers, especially in HCC, it was shown to promote tumor cell proliferation, invasion, metastasis through activation of NF-κB and PI3K/AKT signal pathways." (PMID 29022910, 2017). "Intestinal epithelial cells express TLRs which utilize two adaptors, MyD88 and/or TICAM-1, as well as immune cells and tumor cells in mice." (PMID 29041928, 2017). "Myd88 was known as a tumor promoter, which has been found in various cancers and was related to tumor development, especially in HCC, Myd88 was shown to promote tumor cell proliferation, invasion, metastasis and correlated with prognosis of HCC patients." (PMID 29022910, 2017). "Increased tumour relapse rates were seen in MyD88-/- mice, and in C57BL/6 mice following anakinra (anti-IL-1) treatment, with MyD88 required for IL-1 receptor signalling." (PMID 27100888, 2016). "Fanny Chalmin demonstrated that mice tumor-derived exosomal HSP72 induce IL-6 production by MDSCs through activation of TLR2 and its adaptor MyD88, leading to Stat3 phosphorylation and the promotion of MDSC immunosuppressive functions." (PMID 27090786, 2016). "MC57-SIY tumor cells were injected into MyD88-KO mice and wildtype controls both on the C57BL/6 background, and tumor growth was measured over time." (PMID 25648675, 2015). "Expression of MyD88 was elevated in more than 70 % of patients with EOC and has been considered as an indicator of tumor metastasis and paclitaxel chemoresistance, in addition to a factor for significantly poor prognosis." (PMID 26223974, 2015). "MCF7, PC3, and M628 tumor cells were transfected with lenti-shRNAs specific for TLR8, MyD88, or IRAK4 molecules, or control lenti-shRNA, and then their ability to induce T-cell senescence in the presence of Poly-G3 was determined." (PMID 25231413, 2014). "In the present study, we aimed to investigate the function of TLR4/MyD88 signaling in tumor progression in both cell lines MDA-MB-231 and MCF-7, especially in tumor metastasis." (PMID 25299052, 2014). "Knockdown of TLR8, MyD88, and IRAK4 in tumor cells significantly blocked the Poly-G3-mediated reversal of tumor-induced CD4+ T-cell senescence." (PMID 25231413, 2014). "They showed that TLR4 and MyD88 were expressed in tumor cells of OEC both at the mRNA and protein level, and that the TLR4 induces NF-κB activation in MyD88-positive OEC cells." (PMID 22985132, 2012). "In tumor samples, TLR4 was found to localize to the cell membrane and cell cytoplasm and MyD88 localized to the cell cytoplasm only." (PMID 22583829, 2012). "MyD88 also appears to play a pivotal role in melanoma exosome-mediated MDSC expansion and tumor metastasis." (PMID 22190973, 2011). "In addition, multiple MyD88-related pathways were enriched, supporting prior evidence that CDK4/6 inhibitors can reprogram the tumor microenvironment by modulating the IL-33–MyD88 axis, therefore inhibiting suppressive immune cells." (PMID 40856900, 2025).